GLRX (glutaredoxin)
Description:
Has a glutathione-disulfide oxidoreductase activity in the presence of NADPH and glutathione reductase. Reduces low molecular weight disulfides and proteins.
Synonyms: GRX; GRX1
Tractability: Small molecule: a structure with a bound ligand is known. PROTAC: ubiquitination databases record sites on it; its protein half-life has been measured.
Gene: Protein-coding gene on chromosome 5 (95,751,319 to 95,822,734, reverse strand). Ensembl gene ENSG00000173221.
Subcellular location: Cytoplasm
Subcellular location (Human Protein Atlas): Cytosol; Plasma membrane
Pathways (Reactome):
Metabolism: Interconversion of nucleotide di- and triphosphates
Gene Ontology:
Molecular function: glutathione disulfide oxidoreductase activity; protein binding; sodium channel regulator activity; disulfide oxidoreductase activity
Biological process: positive regulation of membrane potential; nucleobase-containing small molecule interconversion
Cellular component: cytosol; extracellular exosome; cytoplasm; nucleus
Genetic constraint (gnomAD): Loss-of-function variants: 5 observed, 6.43 expected, observed/expected ratio (o/e) 0.78, 90% interval 0.4 to 1.58. That is too few expected variants to judge how well the gene tolerates losing a copy. Missense variants: 70 observed, 86.17 expected, observed/expected ratio (o/e) 0.81, 90% interval 0.67 to 0.99. Synonymous variants: 30 observed, 33.28 expected, observed/expected ratio (o/e) 0.9, 90% interval 0.67 to 1.22.
Homologues: Orthologues: chimpanzee GLRX (100% identical), macaque GLRX (98% identical), mouse Glrx (90% identical), rat Glrx (89% identical), guinea pig GLRX (85% identical), dog GLRX (74% identical), rat Glrx-ps16 (58% identical), zebrafish glrx (58% identical), Caenorhabditis elegans glrx-10 (44% identical), tropical clawed frog glrx (35% identical).
Diseases named in the same sentence as GLRX in open-access papers:
GLRX is named in the same sentence as 106 diseases in open-access papers, as found by Europe PMC text mining. Sharing a sentence is not in itself a finding about the gene and the disease. The quoted sentences say what the papers report.
diabetes (8 papers, 2015 to 2024). "The increased tumor progression in diabetes mellitus may be associated with GLRX upregulation." (PMID 35326089, 2022). "Moreover, the monothiol Grx3 and 5 might link the glutaredoxin system to diabetes through the iron metabolism, mitochondrial dysfunction, and ferroptosis." (PMID 38377787, 2024).
Parkinson disease (6 papers, 2008 to 2024). A progressive degenerative disorder of the central nervous system characterized by loss of dopamine producing neurons in the substantia nigra and the presence of Lewy bodies in the substantia nigra and locus coeruleus. "GLRX is associated with a wide variety of diseases such as Parkinson’s disease, non-alcoholic fatty liver disease, lung disease, and AS." (PMID 36685865, 2022). "NRF1 promotes m6A modification and IGF2BP2‐dependent stability of GLRX mRNA by increasing the expression of METTL3 and leads to the increase of GLRX expression, thus alleviating motor dysfunction and dopamine neuron degeneration in Parkinson's disease mice." (PMID 37735974, 2024).
atherosclerosis (5 papers, 2017 to 2025). A disease characterized by the build-up of fatty material and calcium deposition in the arterial wall resulting in partial or complete occlusion of the arterial lumen. "Glutaredoxin 1 protects mice against obesity and atherosclerosis under nutrient stress in a sex-specific fashion." (PMID 40004248, 2025). "Though increasing evidence has suggested the important roles of oxidative stress in atherosclerosis, few studies have revealed the role of GLRX in atherosclerosis and the formation of FCs." (PMID 33240650, 2020). "GLRX, RNF13, and ABCA1 might be potential targets for atherosclerosis treatment." (PMID 33240650, 2020).
breast carcinoma (4 papers, 2013 to 2023). "For example, GLRX, SNAP23 and OLR1 are overexpressed, which is related to aggressive metastasis in breast cancer and prostate cancer tissues." (PMID 38017548, 2023). "OLR1, GLRX and SNAP23 were overexpressed in human prostate and breast cancer tissues and high expression levels of these molecules are associated with aggressive phenotype and metastatic stage." (PMID 23292678, 2013).
colorectal cancer (4 papers, 2023 to 2025). A primary or metastatic malignant neoplasm that affects the colon or rectum. "Another study conducted in patients with HCC and liver metastases from colorectal carcinoma investigated the expression levels of thioredoxin and glutaredoxin proteins belonging to the thiol oxidoreductase family." (PMID 41393733, 2025). "Published results indicate that PPP2R5E, PES1, RRM2B, GLRX, and CRKL are important in the prognosis and development of colorectal cancer." (PMID 37895091, 2023).
glioma (4 papers, 2020 to 2025). A benign or malignant brain and spinal cord tumor that arises from glial cells (astrocytes, oligodendrocytes, ependymal cells). "In gliomas, high GLRX expression is associated with aggressive subtypes (wild-type IDH, methylated MGMT) and is involved in immune modulation." (PMID 41373732, 2025). "Its coding gene GLRX is an independent prognostic factor in glioma, and closely associates with an immunosuppressive tumor microenvironment with GLRX being precisely expressed in the M0 macrophages." (PMID 37252189, 2023). "Glutaredoxin, a redox regulator, and its encoding gene GLRX were shown to be specifically expressed in macrophage M0, interferes with immune checkpoint function and inflammatory response in glioma, corresponding to worse survival in patients." (PMID 37173373, 2023). "We found that GLRX expression was highly enriched in IDH wild-type glioma patients compared with those harboring IDH mutations." (PMID 33329553, 2020). "Additionally, GLRX is involved in inflammatory activities known to promote glioma progression via activation of tumor-associated macrophages." (PMID 33329553, 2020). "GLRX was significantly upregulated in the mesenchymal subtype of glioma compared with the other three subtypes in the CGGA, TCGA, and CGGA (2019) databases." (PMID 33329553, 2020). "We aimed to elucidate the role of glutaredoxin at the transcriptome level and its clinical prognostic value in glioma." (PMID 33329553, 2020). "Regarding the MGMT promoter status in the CGGA database, we found that gliomas with a methylated MGMT promoter had lower GLRX expression compared to those in the unmethylated group." (PMID 33329553, 2020). "To investigate the role of GLRX in gliomas, we compared the expression levels of GLRX between normal brain tissue and GBM (grade IV, according to the World Health Organization [WHO])." (PMID 33329553, 2020). "The analysis revealed that higher GLRX expression was positively correlated with enrichment of macrophages in glioma tissue." (PMID 33329553, 2020). "Further CIBERSORT analysis revealed that a higher expression level of GLRX is correlated with enrichment of macrophages in glioma tissue." (PMID 33329553, 2020). "GO analysis revealed that GLRX plays a crucial role in immune and inflammatory responses in gliomas." (PMID 33329553, 2020). "Among samples from the CGGA database, GLRX expression was higher in GBM (grade IV) compared with glioma (grades II and III)." (PMID 33329553, 2020). "All these findings collectively confirm that GLRX plays an important role in immune response in gliomas." (PMID 33329553, 2020). "As expected, GLRX expression was significantly upregulated in higher malignant pathological grades of gliomas." (PMID 33329553, 2020). "GLRX is also shown to be an independent prognostic factor in glioma." (PMID 33329553, 2020). "Last, we found that GLRX is an independent prognostic factor in glioma." (PMID 33329553, 2020). "Based on the results of our present study, we hypothesize that GLRX is a potential target for redox and immunotherapy of gliomas." (PMID 33329553, 2020). "Thus, our study establishes GLRX as a novel potential target to enhance the efficacy of anticancer therapies, thereby paving the way for novel therapeutic approaches for treating gliomas." (PMID 33329553, 2020). "We performed GO analysis to identify the GLRX-related biological functions in gliomas." (PMID 33329553, 2020). "Moreover, we also found that GLRX expression was significantly higher in glioma patients with malignant molecular phenotypes, including those harboring the IDH wild-type state, 1p/19q non-codeletion state, and MGMT unmethylated promoters." (PMID 33329553, 2020). "Furthermore, GLRX was found to be significantly enriched in the mesenchymal glioma subtype with GLRX negatively mediating the T cell response and playing a suppressive role in the antitumor immune response." (PMID 33329553, 2020).
glioma (continued). "Additionally, we also analyzed the role of GLRX in the glioma inflammatory response in these databases." (PMID 33329553, 2020). "The results indicated that GLRX had a strong positive correlation with these inhibitory immune checkpoint molecules and that GLRX may influence their expression to support glioma cells escaping immunological surveillance." (PMID 33329553, 2020). "Therefore, GLRX may be upregulated and involved in the immunosuppressive microenvironment of gliomas via modulation of the cellular component of the immune system." (PMID 33329553, 2020). "Therefore, GLRX-targeted cell redox regulatory therapy may enhance response to immunotherapy in patients with glioma." (PMID 33329553, 2020). "In addition, IHC staining was conducted to explore the expression of GLRX in glioma tissues." (PMID 33329553, 2020). "Thus, unraveling the mechanism of GLRX in gliomas may pave the way for the development of novel therapeutic approaches to fight this deadly malignancy." (PMID 33329553, 2020). "Furthermore, GLRX was highly enriched in mesenchymal subtype gliomas." (PMID 33329553, 2020). "In glioma, the role of its coding gene (GLRX) remains unclear." (PMID 33329553, 2020). "As a result, GLRX may serve as a potential prognostic predictor for glioma patients." (PMID 33329553, 2020). "Therefore, GLRX-targeted cell redox regulatory therapy may enhance the efficacy of glioma immunotherapy." (PMID 33329553, 2020). "Moreover, GLRX could be a potential marker for the mesenchymal molecular subtype of gliomas." (PMID 33329553, 2020). "GLRX was found to be highly enriched in gliomas of higher grades with wild-type IDH, without 1p/19q co-deletion, and with a methylated MGMT promoter." (PMID 33329553, 2020).
Hyperglycemia (4 papers, 2015 to 2024). An increased concentration of glucose in the blood. "Furthermore, hyperglycemia led to a reduction in key mitochondrial antioxidant enzymes, including catalase, glutaredoxin, thioredoxin reductase (TrxR), and peroxiredoxin." (PMID 38818468, 2024).
Obesity (4 papers, 2020 to 2025). Accumulation of substantial excess body fat. "Indeed there is ample evidence that metformin administration can ameliorate skeletal muscle loss and function due to glutaredoxin-1 deficiency, obesity, or sarcopenia." (PMID 37185725, 2023).
type 2 diabetes (4 papers, 2015 to 2024). "There is evidence that GLRX expression increases in atherosclerotic coronary arteries and patients with type 2 diabetes, suggesting that the upregulation of GLRX expression might contribute to inflammation and oxidative stress." (PMID 36685865, 2022).
Alzheimer disease (3 papers, 2023 to 2025). A progressive, neurodegenerative disease characterized by loss of function and death of nerve cells in several areas of the brain leading to loss of cognitive function such as memory and language. "GLRX has been associated with autism, cognitive aging in healthy people and amyloid‐β neuropathology in Alzheimer's disease." (PMID 37469193, 2024).
asthma (3 papers, 2020 to 2023). "Protein glutathionylation in lungs is associated with airway inflammation and fibrosis, while glutaredoxin seems to be beneficial in ablating inflammatory responses triggered by asthma initiators." (PMID 37507901, 2023).
glioblastoma (3 papers, 2020 to 2025). The most malignant astrocytic tumor (WHO grade IV). "SP reduced the glutaredoxin activity in U87 glioblastoma cells; however, significant effects were observed when cells were exposed to SP (400 nM)." (PMID 34917417, 2021). "SP reduced glutaredoxin expression in U87 glioblastoma cells; however, significant effects were observed when cells were exposed to SP (400 nM)." (PMID 34917417, 2021). "We started by checking the expression of GLRX in glioblastoma tissue compared with normal brain tissue." (PMID 33329553, 2020). "To further investigate the redox-modulating properties of SP and aprepitant in U87 glioblastoma cells, we evaluated the mRNA expression levels of glutaredoxin enzyme in response to SP (100 and 400 nM) alone or in combination with aprepitant (15 μM) using quantitative RT-PCR." (PMID 34917417, 2021). "Moreover, CLO inhibits growth and inhibits genes related to OS defense (thioredoxin peroxidase, glutaredoxin, nitric oxide oxidoreductase, cytochrome c peroxidase and b5 reductase, GPx, SOD1, SOD2, and CAT) in glioblastoma patient biopsy-derived cell cultures." (PMID 41154163, 2025).
liver fibrosis (3 papers, 2022 to 2025). "Previous research has indicated that reduced GLRX expression exacerbates liver fibrosis, with observed decreases in GLRX and increases in PSSG in fibrotic mice and human liver samples." (PMID 40052788, 2025).
lung carcinoma (3 papers, 2021 to 2025). "As noted in lung cancer cells, the antioxidant gene of GLRX, a regulator of the HIF‐1,114 is associated with treatment resistance, in which their overexpression may result in treatment failure." (PMID 40385549, 2025).
prostate carcinoma (3 papers, 2021 to 2023). A carcinoma that arises from epithelial cells of the prostate gland. "The upregulation of lipid metabolism genes such as oxidized low-density lipoprotein receptor 1 (ORL1), glutaredoxin (GLRX) are characteristics of breast and prostate cancer." (PMID 34940418, 2021). "Prostate cancer progression has been linked to high-level expression of lipid metabolism genes (e.g., OLR1, GLRX and SNAP23) which could contribute to the dysregulation of lipid distribution in the tumor cell membrane." (PMID 35631014, 2022).
autism (2 papers, 2012 to 2024). Persistent deficits in social interaction and communication and interaction as well as a markedly restricted repertoire of activity and interest as well as repetitive patterns of behavior. "Interaction models confirmed a significant association between CTH, glutaredoxin and glutaredoxin 3 and autism (OR = 3.78 (95% CI 2.36-6.04)." (PMID 22524510, 2012).
Colon Cancer (2 papers, 2021 to 2024). "Moreover, by inducing expression of the major intracellular enzyme with deglutathionylase activity, glutaredoxin 1, Jeon and coworkers confirmed the relevance of HIF-1α glutathionylation for its activity in colon cancer cells." (PMID 33937322, 2021).
endometriosis (2 papers, 2024 to 2025). The growth of functional endometrial tissue in anatomic sites outside the uterine body. "Indicative of a higher state of cellular stress, we also found that the decidualizing cells of donors with endometriosis displayed higher expression of stress response genes, such as CRYAB, HSD11B1 and GLRX." (PMID 38402336, 2024).
HIV-1 infection (2 papers, 2012 to 2015). The type species of lentivirus and the etiologic agent of acquired immunodeficiency syndrome (AIDS). "In yet another study, it was shown that another member of the Trx superfamily, glutaredoxin-1 (Grx1), can reduce disulfide bonds in both CD4 and gp120, and its inhibition results in reduced HIV-1 infection." (PMID 23206338, 2012).
idiopathic pulmonary fibrosis (2 papers, 2021 to 2022). Idiopathic pulmonary fibrosis (IPF) is a nonneoplastic pulmonary disease that is characterized by the formation of scar tissue within the lungs in the absence of any known cause. "Glutaredoxin is widely expressed in human lung tissue, including in samples from healthy lung, parenchymal sarcoidosis, extrinsic allergic alveolitis and usual interstitial pneumonia but also in cell lines derived from the lung." (PMID 33932870, 2021).
injury (2 papers, 2021 to 2023). Damage inflicted on the body as the direct or indirect result of an external force, with or without disruption of structural continuity. "GLRX participates in the redox process of various cells by regulating protein S-sulfonylation and is closely related to the occurrence and development of various diseases, such as cardiovascular disease, acute lung injury, ischemia/reperfusion injury, and nonalcoholic fatty liver (NAFL)." (PMID 36818541, 2023).
aortic aneurysm (1 paper, 2023). A ruptured aneurysm located in the wall of the proximal portion of the descending aorta proceeding from the arch of the aorta. "Recent scRNA-seq analysis of aortic aneurysms revealed that GLRX is expressed on SMCs." (PMID 36818541, 2023).
atrial fibrillation (1 paper, 2025). A disorder characterized by an electrocardiographic finding of a supraventricular arrhythmia characterized by the replacement of consistent P waves by rapid oscillations or fibrillatory waves that vary in size, shape and timing and are accompanied by an irregular ventricular response. "Ultimately, by taking the intersection of the results from the three machine learning methods, we identified six feature genes in sepsis: CD81, CLU, GLRX, CKAP4, DPEP2, and BCL11B; and seven feature genes in atrial fibrillation: LDHB, CD81, PFKFB2, CKAP4, CXCR4, DPEP2, and RORA." (PMID 41359645, 2025).
autism spectrum disorder (1 paper, 2012). A spectrum of developmental disorders that includes autism, and Asperger syndrome. "Several SNPs located in the genes for cystathionine γ-ligase (CTH), alcohol dehydrogenase 5, GCL and glutaredoxin showed significant or suggestive associations with autism spectrum disorders." (PMID 22524510, 2012).
dysplastic nevus (1 paper, 2022). Clinically atypical nevi (usually exceeding 5 mm in diameter and having variable pigmentation and ill defined borders) with an increased risk for development of non-familial cutaneous malignant melanoma. "GLRX is decreased in metastatic melanoma compared to dysplastic nevus." (PMID 35326089, 2022).
epilepsy (1 paper, 2011). A brain disorder characterized by episodes of abnormally increased neuronal discharge resulting in transient episodes of sensory or motor neurological dysfunction, or psychic dysfunction. "Since epilepsy is a major feature of Menkes disease, and seizures occur at low frequency in patients affected by Wilson disease, it is conceivable that reduced function of GLRX may lead to increased neuronal excitability." (PMID 21858011, 2011).
hepatoblastoma (1 paper, 2021). Hepatoblastoma (HB) is a malignant hepatic tumor and is the most common pediatric liver cancer. "The overexpression of NOS3 and concomitant NO mediate antiproliferative effects in hepatoblastoma cells through the modulation of the redox state of thioredoxin (Trx) and glutaredoxin (Grx)." (PMID 34200849, 2021).
laryngeal carcinoma (1 paper, 2025). Carcinoma that arises from the laryngeal epithelium. "In this case, increased GLRX expression and impaired mitochondrial activity may collectively regulate the oxidative and hypoxic behavior (i.e., increased HIF1A) exhibited by the resistant laryngeal cancer cells." (PMID 40385549, 2025).
leukaemia (1 paper, 2016). "Glutaredoxin (GRX) is a redox-regulating protein putatively associated with neoplastic process in a human leukaemia HL-60 cell line." (PMID 27250028, 2016).
malignant glioma (1 paper, 2020). A grade III or grade IV glioma arising from the central nervous system. "Altogether, our study outcomes show that GLRX is highly enriched in malignant gliomas and is closely related to the tumor immune microenvironment." (PMID 33329553, 2020). "Altogether, these findings suggest that GLRX is highly enriched in malignant gliomas and is closely related to the tumor immune microenvironment." (PMID 33329553, 2020).